YWHAB (tyrosine 3-monooxygenase/tryptophan 5-monooxygenase activation protein beta)
Diseases named in the same sentence as YWHAB in open-access papers:
YWHAB is named in the same sentence as 28 diseases in open-access papers, as found by Europe PMC text mining. Sharing a sentence is not in itself a finding about the gene and the disease. The quoted sentences say what the papers report.
lung carcinoma (6 papers, 2020 to 2025). "Both the expression of YWHAB and miR-129-5p were associated significantly with prognosis (overall survival) in patients with lung cancer." (PMID 31949489, 2020). "The results showed that higher YWHAB expression was associated with a worse overall survival for patients with lung cancer." (PMID 31949489, 2020). "As expected, increased expression of YWHAB is associated significantly with an unfavorable prognosis (survival) in patients with lung cancer." (PMID 31949489, 2020). "Higher YWHAB expression was associated with a worse overall survival for patients with lung cancer." (PMID 31949489, 2020). "For example, miR-129-5p can regulate the expression of COL1A1 so as to promote the progression of gastric cancer, regulate YWHAB to affect the progression of lung cancer, and target ETV1 to inhibit prostate cancer proliferation." (PMID 36193492, 2022). "The expression level of YWHAB was significantly upregulated in patients' serum with lung cancer compared the normal control." (PMID 31949489, 2020). "Overexpression of miR-129-5p promotes VP16-induced lung cancer cell apoptosis and YWHAB was shown to be a direct downstream target of miR-129-5p." (PMID 31949489, 2020). "YWHAB is a direct downstream target of miR-129-5p and a key mediator of the effects of miR-129-5p in lung cancer cells." (PMID 31949489, 2020). "YWHAB was reported to execute stimulatory roles in the colon, cervical, and lung cancer cells." (PMID 40612667, 2025). "Interestingly, YWHAB was also shown to interact with surfactant protein A2 (SP-A2) and genetic variants of YWHAB can predispose individuals to IPF and lung cancer." (PMID 31900205, 2020). "Ectopic expression of miR-129-5p and YWHAB were found in lung cancer tissue or patients' serum and both of them were closely related to the overall survival of patients, which could be used as biomarkers for monitoring the prognosis of lung cancer patients." (PMID 31949489, 2020). "The correlation of miR-129-5p and YWHAB in lung cancer tissues was also determined." (PMID 31949489, 2020). "Differential expression of YWHAB has been reported in ovarian cancer, lung cancer, breast, and PCa." (PMID 32322560, 2020). "A significant negative correlation between miR-129-5p and YWHAB was found in lung cancer tissues." (PMID 31949489, 2020). "Thus, the YWHAB, YWHAQ, and YWHAZ proteins involved in various biological processes and signalling pathways, could be new targets for future cancer therapy, especially in targeting CSCs in lung cancer." (PMID 33670440, 2021).
breast carcinoma (5 papers, 2016 to 2023). "So, YWHAB is a marker associated with breast cancer metastasis." (PMID 37128318, 2023). "In breast cancer patient blood, YWHAB has significantly higher expression at 7.91 log2 (TPM+1) compared to 7.84 log2 (TPM+1) in healthy samples." (PMID 37128318, 2023). "Overall, SFN, YWHAB, TXNDC12, MYL6B, and PRDX4 expressions are significantly associated with breast cancer patient survival." (PMID 37128318, 2023). "YWHAB plays a key role in cellular proliferation and oncogenic transformation and has been reported to be involved in the development of breast cancer and the activation of tumor/metastasis pathways and inhibition of apoptosis." (PMID 29371858, 2018). "Data extracted from the Human Protein Atlas showed that YWHAB, SFN, and TXNDC12 expression could distinguish early and late-stage breast cancer in various breast cancer subtypes and are associated with poor patient survival." (PMID 37128318, 2023). "High YWHAB expression could significantly predict a worse prognosis in early-stage breast cancer, and its overexpression in luminal A breast cancer has led to a worse prognosis." (PMID 37128318, 2023). "YWHAB, SFN, and MYL6B are upregulated in breast cancer patient's blood, showing biomarker potential." (PMID 37128318, 2023). "A total of three has-miR-542-5p target mRNAs were closely related to overall survival of breast cancer patients in both KMPD and GEPIA, and these are: YWHAB, LY9, and SFRP1." (PMID 29371858, 2018). "Previously, using systems biology approach and cancer signaling networks, we identified top-5 highly expressed and connected proteins (HSP90AB1, CSNK2B, TK1, YWHAB and VIM) in the invasive MDA-MB-231 breast cancer cell line." (PMID 27527857, 2016). "Both YWHAB and SFN are upregulated in breast cancer blood samples and could be found in blood plasma at the highest level of protein certainty." (PMID 37128318, 2023). "Thus, only MYL6B, YWHAB, and SFN expression in breast cancer blood reflected secretory protein expression." (PMID 37128318, 2023). "Therefore, identified upregulated secretory markers YWHAB, SFN, TXNDC12, and MYL6B show strong potential in establishing a battery of breast cancer biomarkers alongside pri-miR526b and pri-miR655." (PMID 37128318, 2023). "Hence, YWHAB and SFN are strong blood-based breast cancer biomarker candidates and tools for understanding TME regulation." (PMID 37128318, 2023). "Regulating the target genes YWHAB, LY9 and SFRP1 may be a possible mechanism of has-miR-542-5p in TamR of breast cancer." (PMID 29371858, 2018). "YWHAB has an oncogenic role in cancer, and SFN (14-3-3σ) is typically documented as a tumor suppressor, although the roles of SFN in breast cancer are not so clear." (PMID 37128318, 2023).
diabetes (3 papers, 2016 to 2022). "Simulated diabetes augmented and reduced the protein levels of PPP2R2B and YWHAB in BCAEC, respectively, which suggest impaired insulin signaling in our model." (PMID 35835939, 2022).
ovarian carcinoma (3 papers, 2020 to 2025). A malignant neoplasm originating from the surface ovarian epithelium. "This set includes eight SASP proteins, for example, 14‐3‐3 protein β/α (YWHAB) and HSP90AB1, which may play a role in apoptosis and inflammation and is a tissue‐specific biomarker of survival in ovarian cancer." (PMID 33512769, 2021).
COVID-19 (2 papers, 2023 to 2024). A disease caused by infection with severe acute respiratory syndrome coronavirus 2. "In the COVID-19 comparison group, five DEPs, PPP1CA, YWHAH, YWHAB, YWHAZ, and TP53BP2, were enriched with the first three upregulated and TP53BP2 downregulated, whereas the PQ group exhibited enrichment only in Smad4 within this pathway." (PMID 39301288, 2024).
epilepsy (2 papers, 2017 to 2021). A brain disorder characterized by episodes of abnormally increased neuronal discharge resulting in transient episodes of sensory or motor neurological dysfunction, or psychic dysfunction. "The remaining group of functional proteins, including YWHAB, YWHAE, YWHAQ, and YWHAZ, that contribute to epilepsy turn out to be encoded by the so-called 14-3-3 family of proteins." (PMID 28255556, 2017). "Consistent with their studies, we also observed downregulation of anti-apoptotic genes (CDKN1A, YWHAB, etc.)and upregulation of pro-apoptotic genes (BCLAF1, etc.)in human epilepsy samples." (PMID 34867172, 2021).
schizophrenia (2 papers, 2020). A major psychotic disorder characterized by abnormalities in the perception or expression of reality. "Interestingly, five of these genes showed alterations in expression in both ASD and schizophrenia: YWHAB, YWHAE, YWHAH and YWHAZ showed decreased expression whether SFN showed increased expression in both disorders." (PMID 32545830, 2020). "However, in line with our results, higher levels of expression of YWHAB, YWHAE, YWHAG and YWHAZ have been described in the brains of schizophrenia patients compared with controls." (PMID 32555255, 2020). "Moreover, an increased expression of SFN and decreased expression of YWHAB, YWHAE, YWHAG and YWHAQ mRNA have been reported in leukocytes of schizophrenia patients." (PMID 32545830, 2020).
Alzheimer disease (1 paper, 2025). A progressive, neurodegenerative disease characterized by loss of function and death of nerve cells in several areas of the brain leading to loss of cognitive function such as memory and language. "Multiple 14-3-3 homologues, YWHAB, YWHAE, YWHAG and YWHAZ, were also found to be consistently upregulated in Alzheimer's disease." (PMID 40491829, 2025).
cervical cancer (1 paper, 2022). A primary or metastatic malignant neoplasm involving the cervix. "As one of the subtypes of the 14-3-3β protein, circSMARCA5 has been found to inhibit the proliferation and invasion of cervical cancer cells by inhibiting the binding of SND1 and YWHAB." (PMID 35795276, 2022).
colorectal cancer (1 paper, 2019). A primary or metastatic malignant neoplasm that affects the colon or rectum. "Further, it has been revealed that B-cell translocation gene (BTG3) knockdown is related to over-expression of multiple genes including YWHAB in colorectal cancer." (PMID 31387239, 2019). "One of the genes, YWHAB, is included in metastatic-prone 54 gene signature for colorectal cancer." (PMID 31387239, 2019).
ductal carcinomas (1 paper, 2007). "Majority of genes encoding proteins with enzyme activity or implicated in metabolism were also upregulated in ductal carcinomas (STK4, SLC1A2, B3GALT3, OSBPL10, CRBN, CHML, YWHAB)." (PMID 17389037, 2007).
idiopathic pulmonary arterial hypertension (1 paper, 2020). A sporadic form of pulmonary arterial hypertension (PAH) characterized by elevated pulmonary arterial resistance leading to right heart failure. "Similar to the other two biomarkers, what role YWHAB plays in the progression of HCC remains a mystery while it proves to be a biomarker for idiopathic pulmonary arterial hypertension (IPAH)." (PMID 33102213, 2020).
Insulin resistance (1 paper, 2023). Increased resistance towards insulin, that is, diminished effectiveness of insulin in reducing blood glucose levels. "YWHAB, as an anti-apoptotic protein, can also cause insulin resistance in cells by affecting mitochondrial polarization." (PMID 37398672, 2023).
lung adenocarcinoma (1 paper, 2021). A carcinoma that arises from the lung and is characterized by the presence of malignant glandular epithelial cells. "The ToppFun FEA, relative to diseases, predicted a possible association of the RAC1, CFH and 5 of the 14-3-3 protein family genes, namely SFN, YWHAB, YWHAE, YWHAG and YWHAZ with lung adenocarcinoma." (PMID 35366267, 2021).
prostate adenocarcinoma (1 paper, 2025). "For instance, YWHAB protein was included in a panel of molecules that contribute to the development of androgen-dependent (LNCaP) and androgen-independent (PC-3) prostate adenocarcinoma cell lines." (PMID 40136513, 2025).
cancer (16 papers, 2016 to 2024). A tumor composed of atypical neoplastic, often pleomorphic cells that invade other tissues. "YWHAB encodes a number of 14–3-3 family proteins, of which 14–3-3β regulates multiple signaling pathways in normal and cancer cells." (PMID 36611208, 2023). "SND1 has been proven in other studies to promote the proliferation and invasion of a variety of cancers, and it can also bind to YWHAB." (PMID 35712125, 2022). "Although YWHAB contributes to the development of cancer, its overexpression has a tumor suppressor effect." (PMID 35712125, 2022). "We have identified a panel of six proteins viz., GOT1, HNRNPA2B1, MAPK1, PAK2, UBE2N, and YWHAB, which contribute to cancer development, and the transition of PCa from androgen dependent to independent stages." (PMID 32322560, 2020). "Unexpectedly, 3 of the 4 genes are from the gene list with prognostic value in > 6 cancers (YWHAB, MCM4, FBXO46)." (PMID 31387239, 2019). "Particularly, the key regulators of mTOR signaling such as LAMTOR2, LAMTOR5, YWHAB, LAMTOR1, FKBP1A, and RHEB were also upregulated in the cancer cells of intra‐tumoral TLS‐low group." (PMID 38498682, 2024). "Moreover, the pathway genes with most links to the query set: MAPK1, MAP2K1, YWHAB, MAP2K2 and MAPK3 are known to be highly expressed in various sorts of cancer, which further highlights the connection to this cancer-derived query set." (PMID 35266519, 2022). "DAVID functional annotation had selected only 4 out of 16 pathways in the A549 CD166 + EpCAM + CSC subpopulation, and 3 pathways in the A549 CD166-EpCAM– non-CSC subpopulation that were related to cancer diseases and that involved the proteins YWHAB, YWHAQ, and YWHAZ." (PMID 33670440, 2021).
tumor (9 papers, 2013 to 2023). "In another proteomics study, the differential expression of YWHAB was quantified using a comparative MALTI/TOF analysis in response to anti-tumor response of retinoic acids." (PMID 31387239, 2019). "YWHAB, a member of the 14-3-3 family of proteins is involved in the activation of tumor/metastasis pathways and inhibition of apoptosis." (PMID 27527857, 2016). "MYC has been deemed both a positive and negative regulator of YWHAB and FN1, hence depending on tissue and tumor type, the regulation of MYC varies." (PMID 37128318, 2023). "After systematic data curation, four upregulated (YWHAB, TXNDC12, MYL6B, SFN) and four downregulated (FN1, PSMB6, PRDX4, PEA15) markers in miRNA-overexpressed tumor secretomes were identified." (PMID 37128318, 2023). "Accordingly, circSMARCA5 can inhibit the interaction of SND1 and YWHAB, and can also reduce the level of SND1, thereby exerting a tumor suppressor effect." (PMID 35712125, 2022). "In our work, the positive correlations between biomarkers and immune cells suggested YWHAB, PPAT, and NOL10 likely related to tumor microenvironment, which affected the recruitment of infiltrating immune cells into the tumor microenvironment of HCC." (PMID 33102213, 2020). "We further knocked down the expression of PPAT, YWHAB, and NOL10 in HCC cells and found that depletion of PPAT, YWHAB suppressed the tumor proliferation." (PMID 33102213, 2020). "Among 17 genes that were included in this panel, the expression of YWHAB, MCM4, LRRC59 and FBXO46 was found to be elevated in tumor tissue compared to normal." (PMID 31387239, 2019). "Several studies have reported the individual expression pattern and function of each hub (TK1, CSNK2B, VIM, YWHAB and HSP90AB1) in different tumors and tumor models in vitro." (PMID 27527857, 2016). "YWHAB, LRRC59 and MCM4 was significantly overexpressed in tumor tissue (p < 0.05)." (PMID 31387239, 2019).
cardiovascular diseases (1 paper, 2024). "FOXO3 and YWHAB are linked to neurodevelopmental disease, while FOXO3 and ANXA2 are associated with cardiovascular diseases." (PMID 38184718, 2024).
metabolic disease (1 paper, 2023). A congenital disorder (due to inherited enzyme abnormality) or acquired (due to failure of a metabolically important organ) disorder resulting from an abnormal metabolic process. "Further studies will be required to identify the specific molecular interactions mediated by YWHAB and how these interactions may advance the development of therapeutic interventions for metabolic diseases." (PMID 38130664, 2023).
neurodegenerative disease (1 paper, 2025). A disorder of the central nervous system characterized by gradual and progressive loss of neural tissue and neurologic function. "Dysregulation of calcium homeostasis is a hallmark of neurodegenerative diseases, and YWHAB’s involvement in calcium signaling pathways may be critical for maintaining neuronal health." (PMID 40626361, 2025).
YWHAB also shares sentences with these, for which no sentence is quoted: gastric cancer (1 paper); glioblastoma (1); hepatocellular carcinoma (1); leukemia (1); osteosarcoma (1); prostate carcinoma (1); psychiatric disorder (1); psychosis (1).